ITGB3 (integrin subunit beta 3)
Diseases named in the same sentence as ITGB3 in open-access papers (continued):
Sharing a sentence is not in itself a finding about the gene and the disease.
renal fibrosis (1 paper, 2021). A final common manifestation of a wide variety of chronic kidney diseases characterized by glomerulosclerosis and tubulointerstitial fibrosis. "It was shown that the semiquantitative IHC expression of ITGB3 was significantly associated with SA-β gal staining and renal fibrosis percentage." (PMID 34805144, 2021). "ISL treatment could suppress Itgb3 expression, attenuate cellular senescence, and prevent renal fibrosis in mice." (PMID 34805144, 2021). "Then, we observed the ITGB3 expression, senescent status, and renal fibrosis in nine DN patients." (PMID 34805144, 2021). "Besides, co-culturing with ITGB3-overexpressed cells could upregulate COL1 and FN1 expression in HK-2 cells, whereas SB525334 could reduce that, suggesting that ITGB3 might induce renal fibrosis related to senescence." (PMID 34805144, 2021).
serous adenocarcinoma (1 paper, 2009). An adenocarcinoma that is characterized by the presence of papillary patterns and cellular budding. "We analysed the gene expression of CLU, ITGB3, CAPG, and PRAME in 30 advanced staged serous adenocarcinomas with quantitative real-time polymerase chain reaction (QPCR) and the protein levels were analysed in 98 serous adenocarcinomas with western blot for semiquantitative analysis." (PMID 19775429, 2009).
silicosis (1 paper, 2021). Silicosis is a respiratory disease caused by breathing in (inhaling) silica dust. "The results indicated that the expression of SMAD2, MAPK3, THBS1, ITGB3, and BMP4 was increased, while the expression of SMAD3 and CD44 was significantly low expression in PBMCs from patients with silicosis, indicating consistent results with the RNA-Seq data." (PMID 34517882, 2021). "Additionally, ITGB3 was higher and CD44 was significantly lower in PBMCs from patients with silicosis compared to health controls." (PMID 34517882, 2021).
sudden sensorineural hearing loss (1 paper, 2022). Sensorineural hearing loss which develops suddenly over a period of hours or a few days. "Itgb3, which encodes the integrin beta chain beta 3, has been previously associated with idiopathic sudden sensorineural hearing loss." (PMID 35454087, 2022).
tendinopathy (1 paper, 2016). "In conclusion, four strong candidate genes (COL11A2; ELN; ITGB3; LOX) were identified as differentially expressed in tendinopathy, functionally linked to features of tendinopathy and implicated in the aetiology of other connective tissue diseases." (PMID 26804977, 2016). "The current study identified four strong candidate genes (COL11A2; ELN; ITGB3; LOX) that are differentially expressed in tendinopathy, functionally linked to features of tendinopathy and previously implicated in the aetiology of other connective tissue diseases." (PMID 26804977, 2016).
thyroid cancer (1 paper, 2018). "In this list, we found that hsa-mir-507 has a corresponding protein complex, corum-1422, and hsa-mir-221-222 cluster regulates nine protein complexes, of which ITGB1, ITGB3 and CD47 were associated with the thyroid cancer." (PMID 29351231, 2018).
thyroid tumor (1 paper, 2024). A benign or malignant neoplasm affecting the thyroid gland. "We then performed a bioinformatic analysis with the cBioPortal program in patients with different types of cancer we verified the existence of the genes ITGAV and ITGB3 (mTR) and found that thyroid tumors are the ones with the highest αv and β3 integrin expression." (PMID 39596225, 2024).
tumor (193 papers, 2009 to 2026). "Loss of ITGB3 signaling promotes immune-suppressive tumor microenvironments by enhancing M2 TAM polarization and function and reducing the number of CD8+ T cells." (PMID 39239559, 2024). "Protein–protein interaction analysis revealed a strong association of ANGPTL proteins with several tumor-suppressor proteins such as ITGB3, ITGAV, and RASSF5." (PMID 37375208, 2023). "Increased ITGB3 expression has been linked to an increase in migration and invasion, as well as a more aggressive phenotype of tumor cells, a progressed tumor grade and a poor prognosis." (PMID 24887580, 2014). "The gene ITGB3 encodes the beta chain of two integral cell-surface glycoproteins, αvβ3 and GPIIb/IIIa, of which αvβ3 is expressed on endothelial and tumour cells." (PMID 19775429, 2009). "Next, we assessed the cell division marker Ki67, which can indicate tumor cell growth, to confirm whether increased ITGB3 expression was associated with tumor cell proliferation." (PMID 36772869, 2023). "ITGB3 plays an important role in vesicle uptake and is closely associated with tumor metastasis." (PMID 36685840, 2022). "In particular, ITGB3 is associated with the tumour progression." (PMID 30559931, 2018). "The loss of ITGB3 expression in tumours from deceased patients and high expression in tumours from survivors could be used as a biomarker for patients with advanced serous tumours." (PMID 19775429, 2009). "Integrin β3 (ITGB3) functions as a pivotal transmembrane receptor mediating bidirectional signalling between cells and the extracellular matrix within the tumour microenvironment (TME)." (PMID 41988207, 2026). "This review systematically elucidates the structure-function relationship of ITGB3, its multidimensional regulatory mechanisms in tumour progression, and current targeted intervention strategies." (PMID 41988207, 2026). "Within this framework, integrin β3 (ITGB3) emerges as a critical extracellular matrix receptor that orchestrates tumor cell adhesion, survival, and drug resistance in cancers like glioblastoma and breast cancer, often through enhanced survival signaling." (PMID 41467954, 2025). "Conditional knockdown of ITGB3 reduces various phenotypes, such as cell migration, proliferation, and senescence, reducing angiogenesis and tumor growth." (PMID 40362482, 2025). "In the subcutaneous tumor model, ITGB3-KD alone mildly inhibited tumor growth, whereas the combination of ITGB3-KD with IR notably suppressed tumor growth." (PMID 40410897, 2025). "High PLAT expression was significantly associated with a poor tumor prognosis, and PLAT was also coexpressed with ITGB3 and TNC." (PMID 39754146, 2025). "This interaction stabilizes ITGB3 protein levels, leading to sustained activation of downstream oncogenic signaling pathways that promote tumor progression." (PMID 41467954, 2025). "Similar to the subcutaneous tumor model, ITGB3-KD alone mildly inhibited tumor growth, whereas the combination of ITGB3-KD with IR resulted in significant suppression of tumor growth." (PMID 40410897, 2025). "We analyzed the correlation of FN1, ITGA4, ITGA5, ITGAV, ITGB1, ITGB3 and ITGB6 with disease status, risk of tumor recurrence according to the 2015 American Thyroid Association guidelines, and patient outcome." (PMID 40423510, 2025). "To further interrogate the role of ITGB3 as a critical downstream effector of STAT3-mediated human tumor initiation in vivo, we performed a limiting dilution assay to compare the ability of FG STAT3WT vs. FG STAT3KO cells to establish tumors in nude mice." (PMID 40701148, 2025). "ITGB3, a member of the integrin family, plays a critical role in tumor progression and microenvironment reprogramming." (PMID 41467954, 2025). "In the orthotopic tibial tumor model, we further validated the radiosensitizing effect of ITGB3-KD in vivo using bioluminescence measurements." (PMID 40410897, 2025).
tumor (continued). "In the eight experimental groups, SERPINA1 knockdown reversed ITGB3 overexpression-induced effects, normalizing PCNA/Vimentin elevation and E-cadherin suppression (P < 0.05), establishing ITGB3 as the primary effector of SERPINA1-mediated tumor progression." (PMID 41467954, 2025). "ITGB3 plays a role in tumor growth by reprogramming tumor metabolism, promoting angiogenesis and cell adhesion." (PMID 40457415, 2025). "The JNKi alleviated the tumor growth inhibition effect induced by ITGB3-KD alone or ITGB3-KD combined with IR." (PMID 40410897, 2025). "Activated macrophages exerted anti-tumor effects by producing inflammatory cytokines like IL-1β, while the interaction between ITGB3 and MFGE8 inhibited macrophage IL-1β production by inducing necrotic cells and an ATP-dependent manner." (PMID 38183097, 2024). "The heterogeneity of tumours underscores the need for personalized medicine, with profiling of ITGB3 expression and TGF-β activity guiding treatment decisions." (PMID 39857240, 2024). "ITGB3 plays a variety of important roles in tumor progression and reprogramming, which can affect angiogenesis through interaction with the microenvironment or small molecules." (PMID 37760946, 2023). "ITGB3 K416 acetylation level was higher in adjacent normal tissues than that of tumor specimens as revealed by IHC staining." (PMID 36453571, 2023). "Immunofluorescent staining revealed a higher level of SIRT2 proteins in NSCLC lung tumor tissues than normal tissues, which inversely correlated with a lower level of ITGB3‐aK416 in NSCLC tumor tissues than normal tissues." (PMID 36453571, 2023). "We further discovered that ITGB3 had a positive correlation with cisplatin resistance through tumor xenografts in mice." (PMID 36772869, 2023). "Our findings indicate that ANGPTL3 and ANGPTL8 play a pivotal role in cancer progression by interacting with tumor-suppressor proteins such as ITGB3, ITGAV, RASSF5, and FNDC5." (PMID 37375208, 2023). "PI3K/AKT has been shown to regulate tumor cell invasion and metastasis by promoting ITGB3 expression." (PMID 37039264, 2023). "Integrin β3 (ITGB3) is one of the β-subunits of integrins, which plays a key role in tumor progression." (PMID 37760946, 2023). "ITGB3 is involved in shaping the stromal and immune microenvironment, reprogramming tumor metabolism and maintaining tumor stem cells and other biological processes." (PMID 37828502, 2023). "In scenarios such as TGF-β induced EMTand tumor-initiating cells, ITGB3 is upregulated, leading to increasedmigration, invasion, maintenance of stemness, and consequent resistanceto targeted therapies." (PMID 37555842, 2023). "ITGB3 is considered a marker of angiogenesis and is involved in the committed steps of tumor angiogenesis by regulating cell–cell and cell–matrix interactions and its involvement in several signaling pathways." (PMID 37760946, 2023). "A CRC-metastasis mice model was constructed via intravenous injection of CT26 cells (1 × 106 cells in PBS) to verify the tumor-promoting effect of ITGB3-rich exosomes." (PMID 37040507, 2023). "Integrin beta 3 (ITGB3) is a member of the integrin family, and it is associated with malignant tumor progression and reprogramming the tumor microenvironment." (PMID 35625561, 2022). "ITGB3 has been reported to play an important role in promoting tumor angiogenesis through enhancing transcriptional activation of VEGFA by β-catenin." (PMID 36130933, 2022). "The data indicated that P-EVs-absorbed NPC cell-transplanted mice presented increased numbers of tumor nodules in the lungs and liver by upregulating ITGB3, suggesting that P-EVs-induced ITGB3 upregulation likely mediate lung and liver metastasis in NPC." (PMID 36263165, 2022). "The β3 integrin (ITGB3) has been reported to play critical roles in tumorigenesis by reprogramming tumor metabolism, promoting angiogenesis, facilitating epithelial to mesenchymal transition (EMT), and maintaining tumor stemness." (PMID 36130933, 2022).
tumor (continued). "More importantly, we found RGD motif is essential for MIIP binding with ITGB3 and executing efficient tumor-suppressing effect." (PMID 36130933, 2022). "ITGB3 acts as a receptor and participates in forming the tumor stromal and immune microenvironment, as well as maintaining tumor stemness." (PMID 35096824, 2021). "Both ITGB1 and ITGB3 have been demonstrated to mediate tumor growth and promote tumor stemness in several tumor types." (PMID 34758833, 2021). "For example, the mRNA expression of CASP9 was down-regulated in tumor tissue compared to marginal tissue, and ITGB3, involved in reactive oxygen species-induced migration and invasion processes, is known to be a malignant indicator in CRC." (PMID 33692961, 2021). "ITGB3 knockdown led to a decreased cellular energy metabolism, suppressed tumor growth, impaired cytokinesis, and migration possibilities, and decreased vesicle trafficking." (PMID 34039961, 2021). "ITGB3 exerts diverse roles in tumor progression and in the reprogramming of the tumor microenvironment." (PMID 34738870, 2021). "The presence of luciferase allowed to start monitoring the tumor size development by bioluminescence imaging (BLI) for measuring the effect of the miRNA mediated ITGB3 knockdown in vivo." (PMID 33083904, 2021). "Simultaneously, the mRNA and protein expression of ITGB3 in tumor tissues increased in HOXA11-AS overexpression mice and decreased in HOXA11-AS silence mice (P < 0.05)." (PMID 34715856, 2021). "Taken together, the light emission of rats treated with a miRNA against ITGB3 decreased uniformly until the detection limit, though the course of tumor regression varied." (PMID 33083904, 2021). "ITGA2B (integrin alpha-IIb;CD41) and ITGB3 (integrin alpha-V beta 3;CD61) can be expressed by CTCs and are critical for the platelet-cancer cell interaction, as inhibition of ITGB3 prevents the platelet-tumour cell interactions." (PMID 33789677, 2021). "Key TGFB activators include integrin proteins, 4 of which (ITGA2, ITGA3, ITGB1, ITGB3) displayed increased expression in the HCC tumor cells (Log2 fold change = −6.16, −5.56, −2.32, and −4.35, respectively)." (PMID 33995488, 2021). "To address this question, we used IHC staining to analyze the expression of HOXB5, CXCR4 and ITGB3 in primary tumor tissues and adjacent non-tumor tissues from two independent CRC patient cohorts." (PMID 33456563, 2021). "The majority of studies claimed ITGB3 acted as a tumor suppressor, due to serials of survival analysis showed ITGB3 highly expressed in OC survivors, siITGB3 in SKOV3 increased cell proliferation, migration, and invasive activity." (PMID 32765584, 2020). "Following on from this, we sought to investigate the mechanisms of cellular ITGB3 in exosome biogenesis and uptake in relation to tumour metastasis." (PMID 32848136, 2020). "The reduced migration observed on fibronectin, for example, hints at tumor cell-ECM interaction regulated by Itgb3 and/or Itgb5." (PMID 32525899, 2020). "Patient age, tumor grade, status of IDH mutation and expression of seven genes (SEMA3A, SEMA3D, SEMA3F, SEMA3G, ITGB3, ITGA5, and VEGFA) significantly correlated with patient OS (p < 0.05)." (PMID 33036421, 2020). "Most of these gene targets are involved in cellular invasion and tumor metastasis by various mechanisms like angiogenesis, cell migration, contact inhibition through ITGB3." (PMID 31832016, 2019). "In vivo, Cal+Cur treatment significantly reduced tumor onset and volume, Itgb3 expression, microvessel count, and tumor uptake of integrin-targeted biosensors, strongly suggesting an antiangiogenic promoting effect of the drug combination." (PMID 31698751, 2019). "Itgb3 is one of the two integrins that forms the αvβ3 receptor in endothelial cells, which plays a crucial role in tumor angiogenesis as inferred from studies showing that targeting αvβ3 resulted in a promising outcome in phase III clinical cancer trials." (PMID 31698751, 2019).
tumor (continued). "One of the limitations of this study is that the effect of ITGB3 downregulation by miR-140-3p needs to be further investigated in a tumor microenvironment containing other cell types such as stromal cells and fibroblasts." (PMID 30559931, 2018). "ITGB3 inhibitors have shown only modest efficacy in patients with advanced solid tumours and in tumour models in vivo." (PMID 29383126, 2017). "Recent study has proved that, by mediating the signal of TGF-beta to MAPKs, β3 Integrin (ITGB3) is recognized as the switching molecule during the phenotypic conversion of TGF-beta from a tumor suppressor to a promoter." (PMID 27374079, 2016). "The treatment with ITGB3 siRNA or the integrin antagonist cilengetide preferentially interrupted the EGFRvIII/integrin β3 complex, effectively reduced tumor cell invasion and activation of downstream signaling effectors." (PMID 26717039, 2016). "By recruiting c-Src to ITGB3 cytoplasmic tail, integrin αvβ3 activated c-Src, substantially increased anchorage-independent tumor cell survival in vitro and metastasis in vivo." (PMID 27833078, 2016). "The products of two differentially regulated integrins, ITGAV and ITGB3, form the αVβ3 heterodimer, an integrin pair previously shown to regulate tumor cell survival and tumor metastasis in a ligand-independent fashion." (PMID 26918447, 2016). "ITGB3 plays an important role in tumor-induced angiogenesis and has been described as a pro-angiogenic factor." (PMID 26506238, 2015). "Genes that are commonly modulated as a result of OPNc overexpression in both OvCar-3 and PC-3 cells (Bcl2l1, Bad, Fos, Itgav, Itgb3, Vegfa and Serpine1) are presumably required for shared functions related to cancer progression in both tumor models." (PMID 24928374, 2014). "The most significant up-regulated genes identified in this tumor model are related to chromosome-end replication (Tert), invasion and metastasis (Plau, Serpine1, Mmp9 and Mmp1), cell adhesion (Itgb3 and Itgav) and angiogenesis (Angpt1 and Vegfa)." (PMID 24928374, 2014). "ITGB3 is a component of integrin αvβ3, which has multifaceted functions in tumor cells including cell growth, adhesion, migration, tumor progression/invasion, growth factor response, and angiogenesis." (PMID 22942880, 2012). "We compared the gene and protein expression levels between tumours from survivors and tumours from deceased patients, and ITGB3 was the one found as differently expressed." (PMID 19775429, 2009). "Only three tumours from survivors expressed ITGB3 less than 0.29 and three tumours from deceased patients more than 0.29." (PMID 19775429, 2009). "In conclusion, ITGB3 was significantly differently expressed between tumours from survivors and tumours from deceased patients." (PMID 19775429, 2009). "The gene and protein ITGB3 (Integrin beta 3) were significantly more expressed in tumours from survivors compared to tumours from deceased patients, which is in concordance with our previous results." (PMID 19775429, 2009). "The expression in tumours from survivors and in tumours from deceased patients were compared, and ITGB3 was significantly more expressed in tumours from survivors (p = 0.004)." (PMID 19775429, 2009). "Our previous analysis demonstrated differences in expression between tumours from survivors and tumours from deceased patients, including four cancer-related genes, ITGB3, CLU, CAPG, and PRAME." (PMID 19775429, 2009). "Among them, ITGB3+ exosome were enriched in Integrin α L, which could promote the proliferation, migration and invasion of tumor cells; whereas ITGAM+ exosome exhibited inhibition of tumor progression and may originate from macrophages." (PMID 41601682, 2026). "Additionally, T2Dexo-PDOs exhibited enhanced extracellular matrix remodeling with heightened interactions involving MMPs (e.g., MMP2—([TGAV + ITGB3]) crucial for tumor cell invasion and migration." (PMID 40858992, 2025).